NPY (neuropeptide Y)
Diseases named in the same sentence as NPY in open-access papers (continued):
Sharing a sentence is not in itself a finding about the gene and the disease.
periodontitis (7 papers, 2018 to 2025). An acute or chronic inflammatory process that affects the tissues that surround and support the teeth. "This is consistent with another genome-wide study, which also shows that single-nucleotide polymorphisms (SNPs) upstream NPY have strong interaction with sex, explaining the risk predilection of severe periodontitis in men." (PMID 36430624, 2022). "Regarding the SNPs associated with periodontal microbes, SNP rs2521634, located near the NPY gene, has been previously associated with the occurrence of severe chronic periodontitis." (PMID 29882907, 2018). "Moreover, a genome-wide association study found suggestive evidence of the association of NPY loci with severe chronic periodontitis." (PMID 36430624, 2022). "A study supports the notion that there is a stimulatory role of gingival crevicular neuropeptide-Y (NPY) in the pathogenesis of periodontitis." (PMID 38196480, 2024). "Elevated NPY levels are present in the GCF of healthy tissues (161 ng) compared to periodontitis-affected tissues (39.8 ng)." (PMID 35978739, 2022). "Five neuropeptides (SP, CGRP, VIP, NKA, and NPY) were assessed to evaluate their role in the pathogenesis of periodontitis." (PMID 35978739, 2022). "Therefore, NPY is significant in both the regulation and the initiation of periodontitis." (PMID 36430624, 2022). "Additional evidence that NPY could be involved in the maintenance of host-microbe homeostasis at the periodontium derives from the observation that NPY levels are higher in human gingival crevicular fluid in healthy conditions when compared to periodontitis." (PMID 29882907, 2018). "The study documented that certain neuropeptides including substance P (SP), NPY, vasoactive intestinal polypeptide (VIP), and more pronouncedly the calcitonin gene-related peptide (CGRP) were positively involved in bone metabolism and periodontitis." (PMID 38196480, 2024). "Also, it has been found that NPY is present in GCF and displays significantly enhanced levels in healthy areas compared to those affected by periodontitis." (PMID 38368525, 2024). "We analyzed studies of any design that compared and evaluated the presence of neuropeptides such as substance P, calcitonin gene-related peptide, neurokinin A, neuropeptide Y, and vasoactive intestinal polypeptide in systemically healthy patients with and without periodontitis." (PMID 35978739, 2022). "Vasoactive Intestinal Peptide (VIP), and Neuropeptide Y (NPY) in saliva (but interestingly not in serum) could potentially be gender-specific salivary biomarkers for periodontitis, regardless of psychological stress." (PMID 31890650, 2019). "SP, CGRP, NPY, and VIP immune reactivity in periodontitis gingiva but no discernable variations in distribution when compared to clinically healthy sites." (PMID 35978739, 2022).
acute kidney injury (6 papers, 2015 to 2025). Sudden and sustained deterioration of the kidney function characterized by decreased glomerular filtration rate, increased serum creatinine or oliguria. "A study reported that when acute kidney injury develops, serum neuropeptide Y levels decrease rapidly in the early stage, and then it can protect the kidney by inhibiting macrophage activation." (PMID 38183438, 2024). "NPY is also indirectly protective against acute kidney injury (AKI) by inhibiting NF-κB-Mincle-mediated M1-macrophage activation and necroinflammation through NPY receptor signalling." (PMID 41325840, 2025). "In acute kidney injury (AKI) mouse models, NPY exhibited renoprotective effects through Y1R by blocking M1 macrophage activation and renal necroinflammation." (PMID 38685911, 2023). "Neuropeptide Y (NPY) derived from osteocytes exhibits renoprotective effects via Y1 receptor-mediated inhibition of NF-κB signaling, which mitigates M1 macrophage polarization and renal necroinflammatory responses during acute kidney injury." (PMID 40735673, 2025).
Arrhythmia (6 papers, 2017 to 2025). Any cardiac rhythm other than the normal sinus rhythm. "Damage to the insular cortex damage is associated with arrhythmia, disruption in diurnal blood pressure variation, myocardial injury, and breathing disorders during sleep, as well as elevated plasma levels of brain natriuretic peptide, catecholamines, and neuropeptide Y (NPY)." (PMID 28758117, 2017). "Neuropeptide Y (NPY) is a sympathetic neurotransmitter that coexists with catecholamines in sympathetic fibres and has been found to play an important role in the changes in arrhythmia pathology." (PMID 34853624, 2021). "Recently, we have identified the sympathetic co‐transmitter neuropeptide‐Y (NPY) as being released during AMI, leading to larger infarcts and life‐threatening arrhythmia in both animal models and patients." (PMID 38847435, 2025).
cholangiocarcinoma (6 papers, 2013 to 2024). A carcinoma that arises from the intrahepatic biliary tree (intrahepatic cholangiocarcinoma) or from the junction, or adjacent to the junction, of the right and left hepatic ducts (hilar cholangiocarcinoma). "On the other hand, in cholangiocarcinoma, NPY diminished proliferation and cellular motility via Y2R." (PMID 36583743, 2023). "NPY blocks tumor cell growth and invasion in cholangiocarcinoma; both effects were counteracted with anti-NPY antibodies." (PMID 37373115, 2023). "More recently, DeMorrow and colleagues have demonstrated that the treatment of cholangiocarcinoma cells with NPY as well as in vitro and in vivo decreases both proliferation and migration." (PMID 24289328, 2013). "Y2R antagonist prevented the anti-proliferative effects of NPY on cholangiocarcinoma growth." (PMID 35087836, 2021).
colon cancer (6 papers, 2013 to 2025). "The neurotransmitter Neuropeptide Y (NPY) is involved in cell motion and cell proliferation and can reduce the invasive potential of colon cancer cells in vitro." (PMID 31731482, 2019). "Furthermore, NPY signaling was shown to regulate angiogenesis in colon cancer and tumor growth and fibrosis in liver cancer." (PMID 40073121, 2025). "NPY can reduce the invasive potential of colon cancer cells in vitro." (PMID 24289328, 2013).
ischemic stroke (6 papers, 2021 to 2025). A stroke disorder caused by obstruction of blood flow to the brain, due to thrombotic (local blood clot formation) or embolic (due to a blood clot or other material traveling from another site) event. "In conclusion, elevated plasma NPY levels in the acute phase of ischaemic stroke were associated with increased risk of major disability, death and major disability at 12 months." (PMID 39575855, 2025). "Subgroup analyses of the association between plasma NPY and the primary outcome in ischaemic stroke patients." (PMID 39575855, 2025). "Several genetic reports have suggested that the C‐399T NPY promoter polymorphism is associated with increased risk for ischaemic stroke." (PMID 39575855, 2025). "Risk of 12‐month clinical outcomes according to plasma NPY quartiles in the acute phase of ischaemic stroke." (PMID 39575855, 2025). "This study aimed to prospectively examine the association between plasma NPY levels and adverse clinical outcomes after acute ischaemic stroke." (PMID 39575855, 2025). "However, there is limited research on the relationship between circulating NPY levels and the risk of adverse clinical outcomes after ischaemic stroke." (PMID 39575855, 2025). "In this large prospective cohort of patients with acute ischaemic stroke, it was found that higher plasma NPY concentrations at baseline were independently associated with greater risk of poor clinical outcome of major disability and death at 12 months after ischaemic stroke onset." (PMID 39575855, 2025). "Elevated plasma NPY levels in the acute phase of ischaemic stroke were associated with increased risk of poor clinical outcomes after ischaemic stroke, suggesting that plasma NPY may be a potential prognostic biomarker for ischaemic stroke." (PMID 39575855, 2025). "Moreover, NPY is decreased in patients with acute ischemic stroke, where NPY polymorphism is correlated with ischemic stroke." (PMID 36338344, 2022). "Korean studies also confirmed that the polymorphism in the C-399T region of the NPY promoter may be an independent risk factor for ischemic stroke." (PMID 34422139, 2021). "This study has important clinical implications for better understanding of the aetiology of ischaemic stroke, and supports NPY as a potential therapeutic target for an important role in the prognostication of ischaemic stroke." (PMID 39575855, 2025). "Further experimental and human investigations are warranted to extend our knowledge of the potential biological mechanism of NPY in ischaemic stroke prognosis." (PMID 39575855, 2025). "To investigate whether HCD and an altered brain flow environment had general effects on NPY expression in the hypothalamus of the complex rat model of experimental ischemic stroke, we checked NPY expression in the hypothalamus using western blot analysis." (PMID 35126096, 2021).
liver cancer (6 papers, 2020 to 2025). An epithelial or non-epithelial malignant neoplasm that arises from the liver. "The same NPY/Y5R pathway stimulated motility of breast and hepatic cancer cells, while high Y5R expression was detected at the invasive edge in liver cancer tissue." (PMID 33681186, 2020). "In liver cancer, NPY accelerates the progression through the transforming growth factor‐β (TGF‐β)/NPY/NPY Y5R pathway." (PMID 41415714, 2025).
memory impairment (6 papers, 2017 to 2025). "In addition, decreases in NPY expression during aging is also associated with learning and memory impairments." (PMID 28161798, 2017). "The decreased expression of CREB-1 and upregulated expression of NPY by mAb 1, mAb 2.5, and mAb 5 group reflects the amelioration of second hit PTZ induced memory impairment." (PMID 33732146, 2020). "This is consistent with the finding in TLE patients that they may experience memory impairment, and suggests that future treatment with NPY gene therapy may not additionally impair their memory." (PMID 33343295, 2020).
neuropathy (6 papers, 2011 to 2024). A disorder affecting the nervous system that manifests with pain, tingling, numbness, and/or muscle weakness. "Since we assume that NPY levels are diminished in the presence of NPY-LA, we hypothesize there is a possible association between NPY-LA levels, neuropathy, gene variants of DCAF5, and the function of ABCC2." (PMID 35627254, 2022). "Future genetic analyses of NPY-LA associations in individuals with T2D, who have neuropathy and vascular disorders, may elaborate on possible associations." (PMID 35627254, 2022). "Recently, NPY overexpression has been proposed to alleviate motor deficits and neuropathy in Machado-Joseph disease (MJD) mouse models, indicating its neuroprotective role in the pathogenesis of MJD." (PMID 35185528, 2022). "Recently, NPY overexpression or intranasal delivery in MJD mouse models have been found to alleviate MJD-associated motor deficits and neuropathy, indicating that NPY has neuroprotective potential in the pathogenesis of MJD." (PMID 35185528, 2022). "Since ARTN was shown to restore expression of multiple neuronal markers in damaged sensory neurons, we studied the effects of BT13 on the expression of IB4, CGRP, and NPY in DRG of rats with experimental neuropathy." (PMID 28680400, 2017). "Studies of NPY-LA with more participants having long-duration T1D and T2D and including identifications of genetic variants are needed to further elaborate associations between DCAF5, ABCC2, NPY-LA, and neuropathies." (PMID 35627254, 2022). "This study aimed to investigate the temporal expressions of activating transcription factor-3 (ATF-3), growth-associated protein-43 (GAP-43), neuropeptide Y (NPY) and galanin in traumatic and non-traumatic rat models of neuropathies associated with NP." (PMID 25070481, 2015). "These neuropathy molecules include CGRP(↓), substance P(↓) and BDNF(↑), neuropeptide Y(↑), galanin(↑) via glial activation, which in turn activates the TNFα, MCP-1 and TLR4 pathways." (PMID 21996269, 2011).
overnutrition (6 papers, 2011 to 2024). An imbalanced nutritional status resulting from excessive intake of nutrients. "In rats, we previously showed that intrauterine and early postnatal overnutrition altered the expression of hypothalamic appetite stimulator neuropeptide Y (NPY) and suppressor pro-opiomelanocortin (POMC) in offspring at weaning." (PMID 21980407, 2011). "We previously demonstrated that intrauterine and early postnatal overnutrition due to litter size reduction altered the expression of NPY and POMC in offspring at weaning, as well as their response to fasting." (PMID 21980407, 2011). "Based on the inhibitory action of Zj7 on the expression of the orexigenic neuropeptides AgRP and NPY, we hypothesized that Zj7 reduces food intake, resulting in improved overnutrition-induced weight gain." (PMID 38570726, 2024). "In a mouse model of diet-induced obesity (DIO), silent AgRP/NPY neurons presented with mitochondria that were increased in size and more elongated than those in wildtypes, demonstrating a role for mitochondrial fusion in AgRP neuronal response to overnutrition." (PMID 33240218, 2020). "It is possible that maternal obesity and overnutrition influenced the hypothalamic synaptic inputs of NPY and POMC neurons, which we did not investigate, rather than neuropeptide expression of NPY and POMC, which we did report." (PMID 32987812, 2020).
polycystic ovary syndrome (6 papers, 2019 to 2026). A disorder that manifests as multiple cysts on the ovaries. "Whether NPY plays a role in pathogenesis of follicular developmental disorders (e.g. polycystic ovarian syndrome) remains to be determined." (PMID 31915051, 2020). "Other studies revealed higher plasma levels of NPY in obese and overweight patients compared to controls, as well as in obese and nonobese women with polycystic ovary syndrome." (PMID 37836499, 2023). "Another possible mechanism of anxiogenic effect of prenatal hyperandrogenemia, not mutually exclusive from the first one, could be the reduction of the number of PV+ and NPY+ neurons in the CA1 region of the hippocampus." (PMID 31281833, 2019).
cardiomyopathy (5 papers, 2016 to 2025). A disease of the heart muscle or myocardium proper. "Transgenic mice with overexpression of NPY are more prone to doxorubicin mediated cardiomyopathy, whereas NPY knockout rats have improved cardiac function and reduced apoptosis following MI." (PMID 38847435, 2025). "We infer from these findings that transport to distal axonal endings and increased release in patients with cardiomyopathy contributes to the higher CS NPY levels seen in these patients compared with control patients (eFigure 3 in the Supplement)." (PMID 31876927, 2020). "Previous studies have shown a diverse role for NPY in different types of cardiomyopathies, including an increase in NPY levels and effects on several pathological processes involved also in DOX-induced cardiotoxicity." (PMID 31811615, 2020). "In mammals, neuropeptide Y has been shown to have several effects on inflammatory responses and cardiomyopathy." (PMID 27769313, 2016).
dementia (5 papers, 2023 to 2024). Loss of intellectual abilities interfering with an individual's social and occupational functions. "Furthermore, NPY has been found to be a regulator of sleep through noradrenergic signaling modulation, which is particularly interesting considering the associations of sleep disruption with the development of dementia." (PMID 38427613, 2024). "The findings revealed that NPY was significantly reduced in patients suffering from dementia of the Alzheimer’s type, with lower concentration observed in more severe stages of the disease." (PMID 39585059, 2024).
eating disorder (5 papers, 2012 to 2021). A broad group of psychological disorders with abnormal eating behaviors leading to physiological effects from overeating or insufficient food intake. "The severity of eating disorder symptoms measured with the EAT-26 scale predicted the concentration of NPY in adolescents across the weight spectrum." (PMID 33670342, 2021). "Correlations between the centrally produced neuropeptide Y and the severity of eating disorder symptoms require further study in this area." (PMID 33670342, 2021). "Taken together, these data suggest that NPY is resistant to the insulin mediated mature IGF-II increase occurring in this eating disorder." (PMID 24386136, 2013). "Increased fasting plasma levels of NPY and obestatin were confirmed in AN and BN groups, which suggest a role of these hormones as a markers for eating disorders." (PMID 22681985, 2012). "The severity of eating disorder symptoms predicted fasting serum concentrations of NPY." (PMID 33670342, 2021). "Significant increase of obestatin and NPY in AN and BN patients may indicate their important role as the markers of eating disorders." (PMID 22681985, 2012). "The severity of eating disorder symptoms measured with the EAT-26 predicted fasting serum concentrations of NPY (p = 0.012) but not PYY." (PMID 33670342, 2021).
fibromyalgia (5 papers, 2010 to 2025). A chronic disorder of unknown etiology characterized by pain, stiffness, and tenderness in the muscles of neck, shoulders, back, hips, arms, and legs. "In cognitive behavioral therapy (CBT), dropping out of NPY levels is accompanied by a reduction in stress among women with fibromyalgia syndrome." (PMID 39202534, 2024). "Crofford and his colleagues were the first to test plasma neuropeptide Y levels in patients with fibromyalgia and found that they were substantially lower in the analyzed patients than in normal subjects." (PMID 33918736, 2021). "A recent study compared 51 fibromyalgia patients to 25 healthy controls and reported elevated plasma NPY." (PMID 21190576, 2010). "In addition, the serum levels of neuropeptide Y were shown to be substantially higher in subjects with fibromyalgia than in healthy controls in two different studies." (PMID 33918736, 2021).
focal epilepsies (5 papers, 2019 to 2024). "NPY levels are increased in epileptic hippocampal samples from animal models and patients with focal epilepsy." (PMID 39251828, 2024). "Gene therapy for focal epilepsy has been a target for focal delivery of galanin or neuropeptide Y (NPY) alone or together with its receptor." (PMID 31486590, 2019). "Based on the accumulating evidence, combinatorial NPY and Y2 receptor overexpression by AAV vectors could be a candidate for gene therapy against focal epilepsies." (PMID 37029201, 2023).
Headache (5 papers, 2012 to 2024). Cephalgia, or pain sensed in various parts of the head, not confined to the area of distribution of any nerve. "Immunohistochemical techniques have been used to compare the expression of signal substances with a putative role in headache pathophysiology (CGRP, substance P, neuropeptide Y, VIP) in tumour tissue in patients with and without pituitary adenoma-associated headache." (PMID 22466226, 2012).